DDB2 (damage specific DNA binding protein 2)
Diseases named in the same sentence as DDB2 in open-access papers (continued):
Sharing a sentence is not in itself a finding about the gene and the disease.
ovarian carcinoma (continued). "Next, we used another human ovarian cancer cell line PEO1 to further examine the coordination between DDB2 and NEDD4L in the regulation of TGF-β signaling transduction." (PMID 26130719, 2015). "Given the function of DDB2 in inhibiting ovarian cancer cell survival and sensitizing ovarian cancer cells to cisplatin treatment, we sought to identify new target genes of DDB2 which function in key signal transduction pathways." (PMID 26130719, 2015). "Here, we report that DDB2-mediated NEDD4L downregulation endowed a significant impact on ovarian cancer cell proliferation through TGF-β signal transduction." (PMID 26130719, 2015). "The analysis of publicly available datasets indicates that low DDB2 mRNA expression correlates with poor outcome of ovarian cancer patients." (PMID 26130719, 2015). "In order to understand the contribution of DDB2 as a tumor suppressor to improved prognosis in human ovarian cancer, we asked what important genes are specifically targeted by DDB2 to affect tumor progression." (PMID 26130719, 2015). "The other protective factor discovered in our study was DDB2, and it was reported that DDB2 could repress ovarian cancer stem cell properties." (PMID 35769257, 2022). "From the analysis performed on the probable miRNAs with an affinity for PLAUR 3’UTR, only miR-328-3p was reported to play stem-related functions maintaining CSC properties in ovarian cancer and enhancing metastasis via the downregulation of the DNA damage binding protein 2 (DDB2)." (PMID 34055629, 2021). "Taken together, these data indicate that DDB2 silencing is able to facilitate the ovarian cancer cell dedifferentiation, characterized by both CD44−CD117− to CD44+CD117+ cell conversions and ALDH− to ALDH+ cell conversions, as well as the non-tumorigenic to tumorigenic cell conversions." (PMID 29752431, 2018). "In addition, DDB2 inhibits tumor growth by various mechanisms, such as limiting the cancer stem cells in ovarian cancer." (PMID 28212551, 2017). "For the DDB2 gene, its under-expression is correlated with poor outcome in ovarian cancer." (PMID 28288164, 2017). "In addition, DDB2 has been shown to suppress the tumorigenicity of both ovarian cancer cells and colorectal cancer cells." (PMID 26130719, 2015). "Thus, by regulating NEDD4L expression, DDB2 enters as a key upstream regulator of the TGF-β signaling cascade in ovarian cancer cells." (PMID 26130719, 2015). "In particular, the connection of DDB2 to the response to signals transduced from extracellular environment provides a new focal point for exploring the contribution of DDB2 to the inhibition of ovarian cancer progression." (PMID 26130719, 2015). "Having established that DDB2 is responsible for NEDD4L transcription repression in human ovarian cancer cells, we asked whether this might be translated into alteration in TGF-β signaling and responses of target genes." (PMID 26130719, 2015). "Our thorough evaluation of the NER protein levels (XPA, XPC, XPF, XPG, ERCC1, and DDB2) and corresponding mRNA levels in various cisplatin-sensitive and -resistant ovarian cancer cell lines revealed that the transcript levels of various NER factors do not accurately reflect their protein levels." (PMID 21385444, 2011). "In addition, the highly expressed DDB2 could enhance the sensitivity of ovarian cancer cells to cisplatin by increasing cell apoptosis." (PMID 35769257, 2022). "Besides, DDB2 participates in sensitizing ovarian cancer cells to cisplatin-mediated apoptosis through the downregulation of the bcl-2 (B-cell lymphoma 2) transcriptional machinery in a HDAC1-dependent (Histone deacetylase 1) manner and the ubiquitylation of the antiapoptotic protein bcl-2." (PMID 31635251, 2019). "NEDD4L, which is transcriptionally repressed by DDB2, enhances TGF-β signaling in human ovarian cancer cells, ultimately inhibiting ovarian cancer cell proliferation." (PMID 38027016, 2023).
ovarian carcinoma (continued). "For instance, DNA damage-binding protein 2 (DDB2) suppresses the expression of NEDD4L and then affects the transforming growth factor-β (TGF-β) signaling in ovarian cancer." (PMID 34869021, 2021). "To this end, we knocked down the expression of DDB2 and ALDH1A1 either separately or simultaneously in the 2008 ovarian cancer cell line, and analyzed the change of CSC abundance phenotypically and functionally." (PMID 29752431, 2018). "The novel mechanism proposes the DDB2-mediated fine-tuning of TGF-β signaling and its downstream effects that impinge upon tumor growth in ovarian cancers." (PMID 26130719, 2015). "The study has uncovered an unappreciated regulatory mode that hinges on the interaction between DDB2 and NEDD4L in human ovarian cancer cells." (PMID 26130719, 2015). "Taken together, these data indicate that NEDD4L is a target gene of DDB2 and DDB2 is capable of downregulating NEDD4L in ovarian cancer cells." (PMID 26130719, 2015). "Due to its role in nucleotide excision repair (NER), it is not surprising that decreased DDB2 expression has been reported in various cancerous tissues, for instance, in prostate, skin, head and neck, and ovarian cancer." (PMID 39335143, 2024). "DDB2 can inhibit the ovarian cancer cell dedifferentiation through downregulation of ALDH1A1; a selective ALDH1A1 inhibitor is able to reduce the tumorigenic CSC subpopulation and halt tumor growth in ovarian cancer cells possessing low levels of DDB2." (PMID 29752431, 2018). "Notably, the MetaGx signature included 3 genes (DDB2, GSTZ1, and FAM1892A) that had been previously identified from the set of 12 genes sharing same-direction hazard ratios in the meta-analysis of breast and ovarian cancers." (PMID 31217513, 2019). "Enhanced ALDH1A1 expression due to DDB2 silencing-induced transcription de-repression plays a critical role in this process, and ALDH1A1 inhibition can block the non-CSC-to-CSC conversion, limit the CSC subpopulation, and halt the tumor regrowth in DDB2-downregulated ovarian cancer cells." (PMID 29752431, 2018). "Notably, DDB2 knockdown (+Dox) enhanced the tumorigenic potential of those CD44−CD117− cells after 12 days of culture, further supporting the role of DDB2 silencing in promoting non-CSC-to-CSC conversions in this ovarian cancer cell line." (PMID 29752431, 2018). "Besides CD44+CD117+ cells, we have also demonstrated that ALDH+ cells isolated from the ovarian cancer cell line 2008 have all known CSC properties including high tumor-initiating capacity, and DDB2 silencing is able to increase the ALDH+ cell population in these cells." (PMID 29752431, 2018). "In addition, other reports have confirmed that the damage-specific DNA binding protein 2 (DDB2) gene, a molecular GGR/NER component that also plays an important role in apoptosis, participates in the sensitivity of platinum-based drugs in ovarian carcinoma cells." (PMID 35052761, 2021). "Given that the CSC subpopulation in a tumor can be maintained by non-CSC dedifferentiation, we attempted to determine whether non-CSC dedifferentiation exists in ovarian cancer cells, and whether DDB2 silencing expands the CSC subpopulation by promoting non-CSC-to-CSC conversions." (PMID 29752431, 2018). "Given that the ALDH1A1 inhibitor NCT-501 can offset DDB2 silencing-induced non-CSC-to-CSC conversions, we reasoned that inhibition of ALDH1A1 activity is also able to reduce the CSC subpopulation and diminish their tumorigenicity in ovarian cancer cells carrying a low level of DDB2." (PMID 29752431, 2018).
xeroderma pigmentosum (20 papers, 2007 to 2025). Xeroderma pigmentosum (XP) is a rare genodermatosis characterized by extreme sensitivity to ultraviolet (UV)-induced changes in the skin and eyes, and multiple skin cancers. "Loss-of-function mutations in human DDB2 cause xeroderma pigmentosum, a disease characterized by hypersensitivity to sunlight and a high risk for skin cancer." (PMID 33575564, 2020). "DDB2 homozygous missense variants are known to cause Xeroderma Pigmentosum group E (MIM: 278,740)." (PMID 37573316, 2023). "Pathogenic mutations in the GGR components XPC and DDB2 (XPE) result in xeroderma pigmentosum (XP) a disease characterised by increased UV-sensitivity and skin cancer incidence." (PMID 26913219, 2015). "The significance of arginine 273 in the WDXR submotif in DDB2 is underscored by its mutation to histidine (R273H) in a xeroderma pigmentosum (XP) group E patient and its failure to bind to DDB1." (PMID 17280619, 2007). "TTD is a distinct condition from Xeroderma Pigmentosum (XP) caused by mutation in eight XP‐associated genes: XPA, XPD (ERCC2), XPB (ERCC3), XPF (ERCC4), XPG (ERCC5), XPC, XPE (DDB2), and a variant form related to the POLH gene." (PMID 39976384, 2025). "Individuals with xeroderma pigmentosum syndrome are deficient in the core NER genes, such as DDB2 and XPC (xeroderma pigmentosum complementation group E and C, respectively), and are susceptible to the development of skin cancer." (PMID 32722430, 2020). "Biallelic pathogenic variants in one of the seven NER genes coding for the so-called complementation groups, XPA, ERCC3, XPC, ERCC2, DDB2, ERCC4, ERCC5, the NER gene ERCC1, and the gene coding for XP variant, POLH, are the causes of the rare hereditary disease Xeroderma pigmentosum (XP)." (PMID 35174087, 2022). "The reduced NER activity may result from the lack of interaction between key lesion recognizer—damaged DNA-binding protein 2 (DDB2) or xeroderma pigmentosum group C (XPC) and PARP1 in the presence of UV damage affecting damage recognition." (PMID 33019598, 2020). "A double heterozygous frameshift and missense pathogenic variant in DDB2 and FANCG genes, respectively were identified in a patient with endometrial cancer, which contrasts to the reported associated phenotype for these variants (Xeroderma pigmentosum and Fanconi anemia, respectively)." (PMID 36428697, 2022). "Exposure to hyperoxic conditions significantly increased the expression of damage-specific DNA binding protein 2 (DDB2) and xeroderma pigmentosum, complementation group C (XPC) in Ctr, CMV-NQO1, NQO1-NQO1, and SNP-transfected cells." (PMID 34691356, 2021). "On the other hand, DNA damage‐binding 1 (DDB1) and DDB2 are recruited in the non-transcribed region to be detected by xeroderma pigmentosum (XP) group E (XPE) in a TCR manner." (PMID 38630271, 2024). "Moreover, ATM and ATR mediate the increase in DDB2 (Damage Specific DNA Binding Protein 2) and XPC (xeroderma pigmentosum, complementation group C)." (PMID 34356109, 2021). "Mutations in seven well characterized NER genes (XPA to XPG), including DDB2 (XPE), result in Xeroderma Pigmentosum (XP), a recessive inherited syndrome characterized by heightened UV-sensitivity, neurological abnormalities, and an increased susceptibility to develop skin cancers." (PMID 24489677, 2014). "The results of immunoblot analyses showed that xeroderma pigmentosum, complementation group C (XPC), and damage-specific DNA binding protein 2 (DDB2) in the NER pathway could not be induced after MMC treatment." (PMID 27833080, 2016).
colon carcinoma (15 papers, 2008 to 2025). "The loss of DDB2 promotes the development of metastatic colon cancer and transformation to a mesenchymal phenotype, increasing the expression of mesenchymal markers N-cadherin and vimentin and decreasing the expression of E-cadherin." (PMID 36190612, 2022). "We previously reported loss of DDB2 expression in high-grade colon tumors of both human and mice origin." (PMID 30410671, 2018). "Indeed, we found that low DDB2 levels are significantly associated with higher survival probability in oxaliplatin-treated colon cancer patients." (PMID 38058548, 2023). "Low DDB2 levels therefore likely represent a specific predictive marker for oxaliplatin treatment in colon cancer." (PMID 38058548, 2023). "Low DDB2 levels predict a significantly better survival when stratifying tumors by DDB2 expression in all 108 oxaliplatin-treated colon cancer patients irrespectively of TNM." (PMID 38058548, 2023). "A lower expression of DDB2, as observed in some of the XPCoxa-inactive cells, can therefore at least partially explain why some colon cancer cells lack an effective GG-NER response to oxaliplatin-induced intrastrand crosslinks." (PMID 38058548, 2023). "We therefore propose that DDB2 is a promising predictive marker of oxaliplatin treatment efficiency in colon cancer." (PMID 38058548, 2023). "Upregulation of DDB2 levels induces the conversion of colon cancer cells with mesenchymal-type to epithelial-type." (PMID 31635251, 2019). "Previous report from our lab showed that DDB2 acts as a barrier to EMT/metastasis in colon cancer cells." (PMID 30410671, 2018). "We also showed that reduced expression of DDB2 in colon cancer cells leads to increased migration/invasion and tumorigenesis." (PMID 30410671, 2018). "EMT is a key regulator of metastasis, and in an orthotropic model of colon cancer in nu/nu mice, we showed that DDB2 blocks metastasis progression." (PMID 30410671, 2018). "DDB2 has been described as down-regulated in high-grade colon cancers moreover, it plays a dominant role as repressor of EMT genes (VEGF, Zeb1 and Snail) in colon cancer cells." (PMID 28061476, 2017). "DDB2 is also able to inhibit metastasis of colon cancer and limit the invasiveness of breast cancer." (PMID 26130719, 2015). "It has been reported that DDB2 affects histone H3 trimethylation status of multiple EMT-related genes in colon cancer." (PMID 26130719, 2015). "Expression of the DDB2 gene has been detected also in some tumor cell lines such as colon carcinoma cell lines and HeLa cells." (PMID 18431487, 2008). "While DDB2 is considered a suppressor of the EMT process in colon cancer cells, recent lines of evidence have indicated that this protein may induce EMT in other types of cancer." (PMID 38773406, 2024). "Strikingly, the only exception was GG-NER, as impairment of XPC or DDB2 had no impact on the sensitivity of DLD-1 colon cancer cells to oxaliplatin, while it did cause hypersensitivity to cisplatin." (PMID 38058548, 2023). "Finally, we show that colon cancer patients with low DDB2 levels have a better prognosis after oxaliplatin treatment than patients with high DDB2 expression." (PMID 38058548, 2023). "Lower DDB2 levels were found in most other XPCoxa-inactive colon cancer cell lines." (PMID 38058548, 2023). "For example, DDB2 is down regulated in metastatic breast and colon cancer." (PMID 30410671, 2018). "The DDB2 protein level is reduced in high-grade colon cancers." (PMID 28212551, 2017). "DDB2 (XPE), is needed for the early steps of NER and is also a regulator of the Wnt/β-catenin signaling in colon cancer cells." (PMID 40001953, 2025). "DDB2 was downregulated in high-grade colon cancer, and low expression of DDB2 inhibited epithelial-to-mesenchymal transition (EMT) of the colon cancer cells, while upregulated the expression of DDB2 inhibited metastasis." (PMID 32090112, 2020).
colon carcinoma (continued). "Our recent studies demonstrated a DNA damage-independent interaction between DDB1/DDB2 and XRCC5/XRCC6 in colon cancer cells." (PMID 30410671, 2018). "For colon cancer, high ERCC3 expression was related to better T stage; ERCC5 expression indicated deeper T stage and distant metastasis; DDB2 expression suggested earlier TNM stage." (PMID 29568775, 2018). "Out of 2000 analyzed genes, DDB2, but not XPC nor HMGA2, significantly associated with hazard ratio of 2.1 in a group of oxaliplatin-treated colon cancer patients." (PMID 38058548, 2023). "Notably, a downregulation of DDB2 was already found in advanced oral/head and neck squamous cell carcinoma (HNSCC) and in colon cancer tissues compared to normal tissues and patients with HNSCC harboring low DDB2 mRNA expression level were associated with a shorter overall survival." (PMID 36568213, 2022). "In colon cancer, DDB2 high expression indicated earlier TNM stage and absence of lymph node or distant metastasis, which was consistent with one cellular research that DDB2 decreased invasion of cancer mainly through inhibiting epithelial-mesenchymal transition (EMT) of colon cells." (PMID 29568775, 2018). "Overall, our data indicated that miR-675-5p promotes tumour progression in colon carcinoma regulating the expression of EMT genes by at least two independent mechanisms: the activation of the transcription factor HIF1α and the inhibition of the repressor factor DDB2." (PMID 28061476, 2017).